SLC38A9 (solute carrier family 38 member 9)
Description:
Lysosomal amino acid transporter involved in the activation of mTORC1 in response to amino acid levels. Probably acts as an amino acid sensor of the Rag GTPases and Ragulator complexes, 2 complexes involved in amino acid sensing and activation of mTORC1, a signaling complex promoting cell growth in response to growth factors, energy levels, and amino acids. Following activation by amino acids, the Ragulator and Rag GTPases function as a scaffold recruiting mTORC1 to lysosomes where it is in turn activated. SLC38A9 mediates transport of amino acids with low capacity and specificity with a slight preference for polar amino acids. Acts as an arginine sensor. Following activation by arginine binding, mediates transport of L-glutamine, leucine and tyrosine with high efficiency, and is required for the efficient utilization of these amino acids after lysosomal protein degradation. However, the transport mechanism is not well defined and the role of sodium is not clear. Can disassemble the lysosomal folliculin complex (LFC), and thereby triggers GAP activity of FLCN:FNIP2 toward RRAGC. Acts as an cholesterol sensor that conveys increases in lysosomal cholesterol, leading to lysosomal recruitment and activation of mTORC1 via the Rag GTPases. Guanine exchange factor (GEF) that, upon arginine binding, stimulates GDP release from RRAGA and therefore activates the Rag GTPase heterodimer and the mTORC1 pathway in response to nutrient sufficiency.
Synonyms: URLC11; FLJ90709; SNAT9
Tractability: Small molecule: a structure with a bound ligand is known. Antibody: UniProt predicts a signal peptide or a membrane-spanning region. PROTAC: ubiquitination databases record sites on it; its protein half-life has been measured.
Gene: Protein-coding gene on chromosome 5 (55,623,437 to 55,773,194, reverse strand). Ensembl gene ENSG00000177058.
Subcellular location: Lysosome membrane; Late endosome membrane
Subcellular location (Human Protein Atlas): Vesicles
Pathways (Reactome):
Signal Transduction: Energy dependent regulation of mTOR by LKB1-AMPK; MTOR signalling; Regulation of PTEN gene transcription; mTORC1-mediated signalling
Autophagy: Macroautophagy
Cellular responses to stimuli: Amino acids regulate mTORC1
Gene Ontology:
Molecular function: amino acid transmembrane transporter activity; cholesterol binding; guanyl-nucleotide exchange factor activity; L-arginine transmembrane transporter activity; L-asparagine transmembrane transporter activity; L-glutamine transmembrane transporter activity; L-leucine transmembrane transporter activity; protein binding; sterol sensor activity; arginine binding; L-amino acid transmembrane transporter activity
Biological process: amino acid transmembrane transport; asparagine transport; cellular response to amino acid stimulus; glutamine transport; L-arginine transmembrane transport; positive regulation of TOR signaling; positive regulation of TORC1 signaling; branched-chain amino acid transport
Cellular component: FNIP-folliculin RagC/D GAP; late endosome; late endosome membrane; lysosomal membrane; lysosome; Ragulator complex
Genetic constraint (gnomAD): Loss-of-function variants: 27 observed, 36.64 expected, observed/expected ratio (o/e) 0.74, 90% interval 0.54 to 1.02. The upper end of that interval is the gene's LOEUF score, 1.02, which puts it in group 4 of 6, group 1 being the genes least tolerant of losing a copy. Missense variants: 333 observed, 443.12 expected, observed/expected ratio (o/e) 0.75, 90% interval 0.69 to 0.82. Synonymous variants: 139 observed, 153.47 expected, observed/expected ratio (o/e) 0.91, 90% interval 0.79 to 1.04.
Gene-disease validity (ClinGen):
ClinGen rates the evidence that SLC38A9 causes each of these diseases.
lysosomal storage disease (inheritance undetermined): No Known Disease Relationship. A metabolic disorder caused by mutations in proteins critical for lysosomal function, including lysosomal enzymes, lysosomal integral membrane proteins, and proteins involved in the post-translational modification and trafficking of lysosomal proteins.
Homologues: Orthologues: chimpanzee SLC38A9 (99% identical), macaque SLC38A9 (99% identical), rabbit SLC38A9 (91% identical), mouse Slc38a9 (91% identical), guinea pig SLC38A9 (89% identical), rat Slc38a9 (88% identical), pig SLC38A9 (88% identical), dog SLC38A9 (87% identical), tropical clawed frog slc38a9 (68% identical), zebrafish slc38a9 (62% identical), Caenorhabditis elegans F13H10.3 (39% identical), Drosophila melanogaster CG32079 (14% identical), and 6 more. Paralogues in human: SLC38A3 (19% identical), SLC38A2 (18% identical), SLC38A5 (16% identical), SLC38A6 (16% identical), SLC38A1 (16% identical), SLC38A4 (16% identical), SLC38A7 (14% identical), SLC36A2 (14% identical), SLC38A11 (14% identical), SLC38A8 (14% identical), SLC36A3 (13% identical), SLC36A1 (13% identical), and 3 more.
Diseases named in the same sentence as SLC38A9 in open-access papers:
SLC38A9 is named in the same sentence as 15 diseases in open-access papers, as found by Europe PMC text mining. Sharing a sentence is not in itself a finding about the gene and the disease. The quoted sentences say what the papers report.
pancreatic cancer (3 papers, 2021 to 2023). "SLC38A9 mediates the transport of essential amino acids out of lysosomes, which is required for the growth of pancreatic cancer cells, and loss of SLC38A9 or its transport function strongly inhibited tumor formation." (PMID 34685533, 2021). "The sensing of an amino acid via SLC38A9 has been reported to be needed in pancreatic cancer cells to form tumors." (PMID 36982390, 2023).
chronic kidney disease (1 paper, 2022). Impairment of the renal function secondary to chronic kidney damage persisting for three or more months. "Finally, the SLC38A9 rs4865615-C variant was significantly associated with a decreased risk of chronic kidney disease." (PMID 36364703, 2022). "Additionally, the SLC38A9-rs4865615 resulted associated with chronic kidney disease." (PMID 36364703, 2022).
Obesity (1 paper, 2024). Accumulation of substantial excess body fat. "A similar effect of obesity was detected in mRNA for Slc38a9, an amino acid (arginine) sensor on lysosomes which aides in mTORC1 regulation, and disassembly of the lysosomal-folliculin complex allowing FLCN GAP activation of RagC." (PMID 38166559, 2024). "Slc38a9 mRNA was unchanged in female mice, but was significantly increased by Obesity in male mice." (PMID 38166559, 2024).
cancer (6 papers, 2016 to 2025). A tumor composed of atypical neoplastic, often pleomorphic cells that invade other tissues. "The regulation of some SLCs, such as SLC7A11, SLC1A5, and SLC38A9, are involved in cancer progression." (PMID 39949345, 2025). "In cancer cells, anabolism dependency on L-arginine via mTORC1 has been associated with the activation of the RAGULATOR-RAG complex in the lysosomal membrane by both SLC38A9 and CASTOR1, the two intracellular sensors of L-arginine." (PMID 36982390, 2023). "SLC38A9 promotes cancer cell proliferation and tumour growth by activating mTORC1, which is commonly activated in tumours and supports biosynthetic needs for the rapid proliferation of cancer cells." (PMID 35810383, 2022). "The present study in abalone demonstrated that SLC38A9 is conservative in regulating the TOR signaling pathway and provided further evidence that SLC38A9 may be used as a promising anticancer target against related cancers." (PMID 34685533, 2021). "Consistent with the apoptosis assay results, we observed that the in vitro growth of cancer cells under amino acid stimulation was reduced by the knockdown of NRF3, SLC38A9, or RagC and by rapamycin treatments." (PMID 36818298, 2023). "This suggests that global metabolism and epigenetics can be controlled by L-arginine in cancer cells via different sensing systems, such as CASTOR1, SLC38A9, and possibly TEAD4." (PMID 36982390, 2023). "Less information are available for six of the genes in the panel in relation to cancer namely the ITPRIP, FRMD6, CPXCR1, SLC38A9, MRPL52 and GFRA4." (PMID 27609023, 2016). "Similarly, the Kaplan–Meier plots of these cancer patients showed a poor prognosis with higher expression levels of NRF3, SLC36A1, SLC38A9, RagC, each RAB5 isoforms, and SLC7A1 genes." (PMID 36818298, 2023).
tumor (6 papers, 2017 to 2023). "Accumulated evidence indicates that SLC38A9 plays important roles in amino acid efflux from lysosomes, mTORC1 activation, and tumor growth using cultured cells and the orthotopic allograft model." (PMID 35457018, 2022). "Cholesterol can increase tumor cell proliferation through activation of the mTORC1 pathway at the lysosomal surface by SLC38A9 (solute carrier family 38 member 9), a lysosomal transmembrane protein that senses cholesterol in addition to arginine, with independent motifs." (PMID 36479100, 2022). "By analyzing TCGA data in the GEPIA database, we found that the expression levels of multiple SLC38A family members (including SLC38A2, SLC38A4, SLC38A5, SLC38A6, SLC38A7, SLC38A8, SLC38A9, and SLC38A10) were significantly upregulated in GC tumor tissues." (PMID 36918802, 2023).
metabolic disorder (1 paper, 2021). "An antagonist of SLC38A9 (NOVELTY) was developed for the treatment of proliferative disease and metabolic disorder associated with TOR activation." (PMID 34685533, 2021).
SLC38A9 also shares sentences with these, for which no sentence is quoted: Alzheimer disease (2 papers); adrenocortical carcinoma (1); colorectal cancer (1); complication (1); Hepatitis (1); liver cancer (1); mesothelioma (1); pancreatic adenocarcinoma (1); Type 2 Diabetes (1).